SARM1 (sterile alpha and TIR motif containing 1)
Diseases named in the same sentence as SARM1 in open-access papers (continued):
Sharing a sentence is not in itself a finding about the gene and the disease.
retinitis pigmentosa (2 papers, 2021 to 2022). Retinitis pigmentosa (RP) is an inherited retinal dystrophy leading to progressive loss of the photoreceptors and retinal pigment epithelium and resulting in blindness usually after several decades. "Recently we identified a role for SARM1 in photoreceptor cell death, consistent with its pro-degenerative function in other neuronal cell types, in a mouse model of the inherited retinopathy retinitis pigmentosa." (PMID 35431772, 2022).
type 2 diabetes (2 papers, 2021 to 2024). "In this study, SARM1 may have potential as a biomarker for the early detection of diabetic peripheral neuropathy in type 2 diabetes patients." (PMID 38400192, 2024).
anterior ischemic optic neuropathy (1 paper, 2024). Anterior ischemic optic neuropathy (AION) is an eye disease characterized by infarction of the optic disk leading to vision loss. "Thus, RGCs from SARM1(−)(−) animals show increased resistance to rNAION-induced acute ischemic optic neuropathy." (PMID 38334594, 2024).
atherosclerosis (1 paper, 2025). A disease characterized by the build-up of fatty material and calcium deposition in the arterial wall resulting in partial or complete occlusion of the arterial lumen. "Consequently, inadequate conversion of NMN into NAD+ results in the accumulation of toxic NMN, ultimately leading to axonal degeneration, and further experiments are needed to determine whether NMN acts through SARM1 in atherosclerosis." (PMID 40143060, 2025).
autosomal dominant optic atrophy (1 paper, 2025). An autosomal dominant hereditary condition characterized by optic atrophy and progressive visual loss. "The researchers built a novel mouse model of Autosomal Dominant Optic Atrophy and showed that knocking out SARM1 strongly suppresses Retinal Ganglion Cell degeneration." (PMID 40344041, 2025).
Brain atrophy (1 paper, 2019). Partial or complete wasting (loss) of brain tissue that was once present. "Collectively, these studies demonstrate that Sarm1 deletion does not influence regional brain atrophy or neuronal loss caused by TDP-43Q331K, and that temporal-lobe equivalent brain regions are more significantly affected by TDP-43Q331K overexpression than the primary motor cortex." (PMID 31661035, 2019).
breast carcinoma (1 paper, 2025). "These metabolites can act through intervening in breast cancer targets such as SARM1, RGS5, BAG1, PROM2, and NEAT1." (PMID 40223933, 2025).
cognitive decline (1 paper, 2024). "Taken together, these results suggested that SARM1 deletion in CNS alleviated cognitive decline, Aβ deposition and inflammatory infiltration in APP/PS1 mice by downregulation of TNF-α signaling." (PMID 37307837, 2024). "Our results showed that the deletion of SARM1 in APP/PS1 AD model mice led to a reduction in Aβ deposition, inflammatory infiltration, and neuronal death, thereby delaying cognitive decline." (PMID 37307837, 2024). "Interestingly, conditional knockout (CKO) of SARM1 in the central nervous system (CNS, SARM1Nestin-CKO mice) delayed the cognitive decline in APP/PS1 AD model mice." (PMID 37307837, 2024).
cone dystrophies (1 paper, 2020). "In this study, we have demonstrated that loss of SARM1 promotes both rod and cone photoreceptor cell survival; therefore, SARM1 presents a novel target for pharmacological inhibition for patients with rod and cone dystrophies." (PMID 32312889, 2020).
cortical atrophy (1 paper, 2019). "Although our studies of the brain demonstrated that TDP-43Q331K-induced cortical atrophy and neuronal loss were not suppressed by Sarm1 deletion, we hypothesised that Sarm1 deletion could still mitigate dendritic spine loss in mutant mice." (PMID 31661035, 2019).
COVID-19 (1 paper, 2024). A disease caused by infection with severe acute respiratory syndrome coronavirus 2. "There was a significant influence of the COVID-19 vaccination doses on the SARM1 level, as two doses of vaccination caused a huge surge in the SARM1 compared to a single dose." (PMID 38400192, 2024). "The changes in SARM1 levels observed following COVID-19 vaccination are interesting, but the clinical significance and long-term implications of these changes are still unclear." (PMID 38400192, 2024). "Two doses of COVID-19 vaccination increased the SARM1 levels by 119.30%, 76.13%, and 143.13% in the HP group, T2DM group, and T2DMN group, respectively, compared with the median of the single-dose group." (PMID 38400192, 2024). "Physiologically and based on our findings, a healthy individual will display increased serum SARM1 levels following COVID-19 vaccination because of the innate immune response." (PMID 38400192, 2024). "Emphasizing the significance of considering the impact of the COVID-19 vaccine on SARM1 levels and its transient nature, as well as the timing of measurements, is crucial for accurately interpreting study results." (PMID 38400192, 2024). "After adjusting for the number of COVID-19 vaccinations, the median serum SARM1 concentration in the T2DMN group was significantly higher than the HP group with a single dose of COVID-19 vaccine (group A)." (PMID 38400192, 2024). "By considering the potential impact of the COVID-19 vaccine on SARM1 levels, researchers can better understand any observed differences or lack thereof between study groups." (PMID 38400192, 2024). "We set out to assess serum SARM1’s activity as a potential biomarker for the early identification of diabetic peripheral neuropathy in T2DM patients while also examining the impact of the COVID-19 vaccine on SARM1 levels." (PMID 38400192, 2024). "However, we thought this sample size showed a significant influence of the COVID-19 vaccination on the SARM1 level, which carries a lot of significance and should guide selection criteria and analysis in future studies." (PMID 38400192, 2024). "We observed pronounced effects of COVID-19 vaccination on the SARM1 level." (PMID 38400192, 2024). "In our study, COVID-19 vaccination was found to cause changes in serum SARM1 levels in both diabetic and non-diabetic individuals." (PMID 38400192, 2024). "There was a significant positive correlation between the SARM1 level with the MNSI-E and NSS in the participants with a single dose of COVID-19 vaccine after adjusting the numbers of COVID-19 vaccine doses." (PMID 38400192, 2024). "Due to the huge surge in the SARM1 level, the correlation was statistically insignificant without consideration of the number of COVID-19 vaccinations." (PMID 38400192, 2024). "However, the effects of antiviral COVID-19 vaccination on the expression of SARM1 were not investigated." (PMID 38400192, 2024).
Crohn disease (1 paper, 2025). A gastrointestinal disorder characterized by chronic inflammation involving all layers of the intestinal wall, noncaseating granulomas affecting the intestinal wall and regional lymph nodes, and transmural fibrosis. "Sarm1-mediated neurodegeneration in the ENS reduces colonic inflammation.Neurodegeneration as a strategy to treat IBD (Crohn’s disease, ulcerative colitis)." (PMID 40145027, 2025).
cystic kidney disease (1 paper, 2012). A congenital or acquired kidney disorder characterized by the presence of renal cysts. "Analyses indicated 13 genes, in addition to Nek8 and Ift20 within this area that could potentially result in cystic kidney disease, namely: RGD1309077Phf12, Flot2, Spag5, Sdf2, Supt6h, Proca1, Traf4, Sarm1, Nlk and Ksr1." (PMID 22899815, 2012).
Dystonia (1 paper, 2025). An abnormally increased muscular tone that causes fixed abnormal postures. "The question of reversibility is also relevant to therapies aiming to activate SARM1 for neuroablation to treat conditions such as spasticity, dystonia and neuropathic pain, because permanent SARM1 activation in these conditions could lead to unwanted effects and lasting disability." (PMID 40473123, 2025).
giant cell arteritis (1 paper, 2024). "Therefore, considering their reasonable potential role in giant cell arteritis pathogenesis, either gene (VTN or SARM1) or a more intricate mechanism influencing both could underlie the observed association within this genomic locus." (PMID 38734017, 2024).
Hyperglycemia (1 paper, 2024). An increased concentration of glucose in the blood. "Unexpectedly, global Sarm1 knockout completely protected female mice from T1D-associated bone suppression and skeletal fragility despite comparable muscle atrophy and hyperglycemia." (PMID 38175722, 2024).
ischemic stroke (1 paper, 2025). A stroke disorder caused by obstruction of blood flow to the brain, due to thrombotic (local blood clot formation) or embolic (due to a blood clot or other material traveling from another site) event. "After PTI, mice showed substantial deficits in the grid-walking and adhesive removal tests, whereas SARM1 deletion improved performance at 3 d post ischemic stroke, and this advantage persisted for 14 d." (PMID 41272776, 2025). "First, we tested whether SARM1 deletion affected behavioral outcomes after ischemic stroke." (PMID 41272776, 2025).
Klebsiella Infections (1 paper, 2022). Infections with bacteria of the genus KLEBSIELLA. "SARM1 inhibition will show a beneficial effect to treat Klebsiella infections." (PMID 35947948, 2022).
melanoma (1 paper, 2022). A malignant, usually aggressive tumor composed of atypical, neoplastic melanocytes. "SARM1 inhibits the activation of Klebsiella-induced absent in melanoma 2 inflammasome to limit IL-1β production, suppressing further inflammation." (PMID 35947948, 2022).
motor neuron degeneration (1 paper, 2019). "Having determined that Sarm1 deletion ameliorated TDP-43Q331K-induced motor neuron degeneration and dendritic spine loss we bred larger cohorts of mice for behavioural studies." (PMID 31661035, 2019).
motor peripheral neuropathy (1 paper, 2022). Inflammation or degeneration of the peripheral motor nerves. "The NMNAT2/SARM1 axon degeneration pathway functions in both sensory and motor neurons; yet, curiously, Nmnat2V98M/R232Q mice primarily develop a motor peripheral neuropathy." (PMID 36287209, 2022).
muscle atrophy (1 paper, 2024). The loss of muscle tissue due to inactivity or disease. "Together, these results reveal that global KO of Sarm1 in females facilitates the maintenance of osteoblast number and function even in a setting of severe T1D-associated metabolic disease and muscle atrophy." (PMID 38175722, 2024).
neuro-degenerative diseases (1 paper, 2025). "SARM1 is a key regulator of a conserved program of axon degeneration increasingly linked to human neuro-degenerative diseases." (PMID 40473123, 2025).
non-alcoholic fatty liver disease (1 paper, 2021). "In the liver of mice suffering from non-alcoholic fatty liver disease (NAFLD) induced by a high fat diet (HFD), SARM1 shows a significant increase in both mRNA and protein levels." (PMID 34307460, 2021).
optic atrophy (1 paper, 2025). A disorder characterized by loss of optic nerve fibers. "We then studied the effect of Sarm1 deletion on the progression of optic atrophy in this mouse model." (PMID 40344041, 2025).
pneumonia (1 paper, 2022). An acute, acute and chronic, or chronic inflammation focally or diffusely affecting the lung parenchyma, caused by an infection in one or both of the lungs (by bacteria, viruses, fungi, or mycoplasma.). "Importantly, these polysaccharides are required for KP survival in mice (pneumonia model), underlining the importance of SARM1 induction as a KP virulence trait since this process is abrogated in these mutant strains." (PMID 35947948, 2022).
Stroke (1 paper, 2025). Sudden impairment of blood flow to a part of the brain due to occlusion or rupture of an artery to the brain. "However, the exact role of SARM1 in neurons of stroke-affected mice in vivo, as well as its underlying mechanisms, requires further investigation." (PMID 41272776, 2025). "We stained microglia cells with Iba1, and evaluated the effects of SARM1 deletion on microglial morphology in the peri-infarct cortex using Image J. Stroke injury caused deramification of microglia, which was defined as shortened projections and enlarged cell bodies." (PMID 41272776, 2025). "In the present study, a mouse model of stroke with focal infarction in the cortex was used to investigate the potential relation between SARM1 and post-stroke brain injury." (PMID 41272776, 2025). "To explore the function of SARM1 after stroke, we examined its expression pattern in the cortex at different time points after PTI." (PMID 41272776, 2025). "Following TTC staining demonstrating reduced brain injury at 3 days post stroke, we further explored the effect of SARM1 deletion on the local tissue inflammatory response." (PMID 41272776, 2025). "We found that SARM1 expression increased in neurons of the peri-infarct cortex at an early stage after photothrombotic stroke induction (PTI) and was evenly distributed between excitatory and inhibitory neurons." (PMID 41272776, 2025). "Consistently, our results showed that Sarm1−/− mice had smaller infarct volumes, better preserved neurons in the peri-infarct area, and superior neurological function in stroke models." (PMID 41272776, 2025). "Our findings suggest that SARM1 is a promising target for post-stroke neuroprotection." (PMID 41272776, 2025). "In summary, our study identified the role of SARM1 in stroke pathophysiology." (PMID 41272776, 2025). "We found that SARM1 deletion promoted neuronal preservation in the peri-infarct cortex and alleviated axonal degeneration, thereby improving behavioral performance after stroke." (PMID 41272776, 2025). "Our findings demonstrate that SARM1 deficiency attenuates ischemic neuronal injury and improves neurological performance post PTI, suggesting that the SARM1 signaling pathway could serve as a potential therapeutic target for stroke in the future." (PMID 41272776, 2025). "Finally, we tested the effects of SARM1 inhibitors in stroke-affected mice to assess their translational value." (PMID 41272776, 2025). "To explore the translational value of this study for patients with stroke, we examined whether inhibition of the SARM1 pathway alleviated cortical injury and improved neurological performance after PTI." (PMID 41272776, 2025). "In this study, we examined the relation between SARM1 expression and post-stroke neuronal injury." (PMID 41272776, 2025). "Therefore, the SARM1 signaling pathway may serve as a promising therapeutic target for stroke treatment." (PMID 41272776, 2025). "Importantly, Sarm1−/− mice exhibited substantial preservation of neurological function for up to 14 d post stroke, indicating that SARM1 loss is neuroprotective rather than merely delaying neuronal and axonal death." (PMID 41272776, 2025). "This suggests SARM1 mediates post-stroke neuronal death primarily through regulating NAD+ metabolism rather than PARP1 activation, providing new insights into targeting SARM1 to protect neurons." (PMID 41272776, 2025). "Additionally, although SARM1 deletion significantly reduced infarct volume and inflammatory response, the specific mechanisms underlying the associated inflammatory changes remain unclear, limiting the ability to fully recapitulate the Sarm1−/− phenotype in a photothrombotic stroke model." (PMID 41272776, 2025). "Collectively, these results indicate that SARM1 is expressed in neurons, upregulated at early stages after PTI, and evenly distributed between excitatory and inhibitory neurons under both physiological and stroke-induced pathological conditions." (PMID 41272776, 2025).
Stroke (continued). "FK866 and DSRM-3716, two recently reported pharmacological inhibitors of SARM1, failed to alleviate brain injury in mice with stroke." (PMID 41272776, 2025). "During the acute phase of stroke, the behavioral improvements observed in Sarm1−/− mice post PTI may be attributed to the neuroprotective effects of SARM1 deletion." (PMID 41272776, 2025). "We observed clear colocalization of SARM1 and NeuN in both the sham-treated and stroke-injured groups, whereas no colocalization was detected between SARM1 and Iba1 or GFAP." (PMID 41272776, 2025). "The results suggest that these two recently reported pharmacological inhibitors of SARM1 failed to mitigate brain injury in mice with photothrombotic stroke." (PMID 41272776, 2025).
type 1 diabetes (1 paper, 2024). "Global knockout of Sarm1 prevented DPN, but not skeletal disease, in male mice with type 1 diabetes (T1D)." (PMID 38175722, 2024).